CYP24A1 (cytochrome P450 family 24 subfamily A member 1)
Diseases named in the same sentence as CYP24A1 in open-access papers (continued):
Sharing a sentence is not in itself a finding about the gene and the disease.
cancer (continued). "The evidence should suggest that a possible way to enhance the anti-cancer activity of vitamin D3 is to increase 1,25(OH)2D3 effect by reducing the inhibitory action of CYP24A1, with molecules such as KD-35 or 4,5,6,7-tetrabromobenzimidazole (TBBz)." (PMID 26301200, 2015). "For example, the most abundant one, located in chromosome 20 and annotated as CYP24A1 exonic circRNA, is expressed in only five cell types and is hundreds of times more abundant in cancer cell A549 compared with the other four cell types." (PMID 25583365, 2015). "Increased levels of CYP24A1 have been observed in some human cancers including colon, breast and lung tumors." (PMID 25334067, 2014). "Locally produced 1,25(OH)2D is assumed to have an anti-cancer effect, and an increased local expression of the CYP24A1 gene (and thereby increased degradation of 1,25(OH)2D) has been associated with poor survival." (PMID 22649517, 2012). "Notably, the catabolic enzyme, CYP24A1, is also upregulated at high dose treatments, which most likely attenuates the anti-cancer action of 25(OH)D3." (PMID 40362248, 2025). "It has been reported that CYP24A1 is upregulated in several cancer types, including CRC." (PMID 39858498, 2025). "CYP24A1 has been identified as a potential biomarker for cancer." (PMID 37670334, 2023). "High expression of CYP24A1 was correlated to incidence of metastasis and recurrence of cancer." (PMID 36527000, 2022). "In the subgroup analysis, cancer type, treatment, ethnicity, and detection approach for CYP24A1 did not affect the significance of the association between CYP24A1 expression and poor prognosis." (PMID 36527000, 2022). "High expression or SNP of CYP24A1 was correlated to drug resistance of cancer patients." (PMID 36527000, 2022). "The subsequent question is whether the correlation between CYP24A1 expression and shorter survival time is varied in different cancer types." (PMID 36527000, 2022). "Since metastasis and recurrence could be correlated to cancer resistance, we calculated and pooled the ORs (odds ratio) of metastasis and recurrence in the CYP24A1 subpopulation to evaluate the effect of CYP24A1 expression on drug resistance." (PMID 36527000, 2022). "Relevant studies detecting the expression or SNP of CYP24A1 in cancer patients up till May 2022 were systematically searched in four common scientific databases including PubMed, EMBASE, Cochrane library and ISI Web of Science." (PMID 36527000, 2022). "Moreover, an analysis of the VDR and CYP24A1 expression of circulating disseminated cancer cells and the corresponding primary cancer tissues would have been interesting for studying the metastatic process more precisely." (PMID 36362766, 2022). "The pooled HRs for all the 3 subgroups were higher than 1 with lower 95% CI also higher than 1, thus suggesting that CYP24A1 expression is significantly associated with poorer prognosis independent of the cancer type." (PMID 36527000, 2022). "CYP24A1 was highly unregulated in various cancer types, including lung, colon, and ovarian tumors." (PMID 36527000, 2022). "The development of calcitriol analogs that show less specificity for CYP24A1 but elicit strong VDR responses could be a solution for the low availability of calcitriol at the cancer site." (PMID 35406562, 2022). "This indicates that high expression or SNP of CYP24A1 in cancers led to a shorter survival time." (PMID 36527000, 2022). "Taken together, CYP24A1 is involved in the regulation of metastasis and sensitivity to inhibitors in cancer cells, which could be a good candidate for targeted cancer therapy." (PMID 36527000, 2022). "This indicates that the SNP of CYP24A1 might influence the expression or function of CYP24A1, which could potentially impact the cancer occurrence and the prognosis of patients." (PMID 36527000, 2022). "Furthermore, it would be interesting to analyse the expression of CYP27B1 and its interactions with VDR and CYP24A1 in cancer cells." (PMID 36362766, 2022).
cancer (continued). "Moreover, the inhibition of CYP24A1 in 1,25(OH)2D3-insensitive cancer cells enhances vitamin D anti-proliferative effects." (PMID 36362766, 2022). "High expression of CYP24A1 was correlated to poor prognosis of cancer patients." (PMID 36527000, 2022). "Summarizing, it seems that overexpression of CYP24A1 may lead to decreased level of calcitriol in cancer." (PMID 34208589, 2021). "Based on these studies, we hypothesized that CYP24A1 may play a crucial role in the pathogenesis of cancer." (PMID 34191826, 2021). "In the present study, We aimed to investigate whether 1α,25(OH)2D3 could suppress the migration and invasion of MOSE cells during malignant transformation, and whether knockdown of CYP24A1 enhances the anti-cancer effects of 1α,25(OH)2D3 by regulating EMT." (PMID 32850381, 2020). "Eldecalcitol can affect the substance of Cyp24A1 expression in the cancer cells." (PMID 33336024, 2020). "Given that CYP24A1 is an enzyme that degrades calcidiol and calcitriol, it is likely that cancer cells may upregulate CYP24A1 expression to reduce local concentrations of calcitriol, which is similar to the reduction of CYP27B1 in some cancers." (PMID 29657326, 2018). "Finally, epigenetic regulation involving the CYP24A1 promoter region contributes to the altered expression of CYP24A1 in cancers." (PMID 29657326, 2018). "In addition, overexpression of CYP24A1 has been also reported in many other cancer types including ovarian, cervical, squamous cell, and basal cell carcinoma." (PMID 29657326, 2018). "Most cancers express not only the VDR but also CYP27B1 and CYP24A1 thus allowing cancer cells to regulate locally 1,25(OH)2D levels, and it has been reported that cancers expressing CYP27B1 tend to be well differentiated while cancers which do not express CYP27B1 tend to be poorly differentiated." (PMID 29951549, 2018). "It has been reported that CYP24A1 may be a candidate oncogene and a potential prognostic biomarker for cancer." (PMID 27834829, 2016). "Increased expression of CYP24A1 in cancer cells may attenuate the effects of 1α,25(OH)2D3 on growth inhibition and differentiation." (PMID 26260259, 2015). "In addition, CYP24A1 has been considered as a putative proto-oncogene and its inhibition is proposed as an adjuvant in vitamin-D based cancer treatment." (PMID 25334067, 2014). "CYP24A1 plays an important role in vitamin D homeostasis in tissues by catabolizing the active form of vitamin D (1,25-D3), which has anti-proliferative effect in cancer, to inactive calcitroic acid." (PMID 25415319, 2014). "SENP1 expression levels have been demonstrated to be elevated during prostate pathogenesis while those of CYP24A1 are increased in cancers of the prostate, colon, ovary, and lung, a number of which are known to be insensitive to the growth-regulatory effects of vitamin D." (PMID 24586832, 2014). "CYP24A1 may thus be a predictive marker of 1,25(OH)2D3 efficacy as an adjunctive therapy in patients with cancer." (PMID 25522365, 2014). "In further analyses stratified by ER status, one SNP in VDR and seven SNPs in CYP24A1 were specifically associated with ER- but not ER+ cancer risk, and the associations differed between AA and EA women." (PMID 22480149, 2012). "Additionally, the downregulation of CYP24A1, a key enzyme in vitamin D catabolism and a biomarker of aggressive cancers, may sensitize cells to vitamin D-based therapies and conventional chemotherapy." (PMID 40756515, 2025). "Importantly, this may be synonymous with the calcipotriol response observed in MG63 cells, which yields both high levels of CYP24A1 and anti-cancer responses at the same time via alternative pathways to 1,25(OH)2D signaling." (PMID 37228489, 2023). "Thus far, there have been various studies revealing an association of CYP24A1 polymorphism with survival of cancer patients who are treated with or without drugs." (PMID 36527000, 2022).
cancer (continued). "However, some of these studies did not assess the function of CYP24A1 SNP in cancer incidence, whereas some studies had showed its opposite function in cancer risk and patient survival." (PMID 36527000, 2022). "Moreover, both of the cell lines were characterized by lower expression of claudin-2 (CLDN2), C-X-C chemokine receptor type 4 (CXCR4), and cytochrome P450 family 24 subfamily A member 1 (CYP24A1), which codify for proteins commonly reported to be associated with cancer progression and invasiveness." (PMID 35159043, 2022). "Due to the Cyp24A1 mRNA expression up-regulation and interaction with the calcitriol anti-proliferative functions, the calcitriol level may decrease to prevent the application of vitamin D3 for the therapy of different cancers." (PMID 33336024, 2020). "CYP24A1 inhibitors, such as the isoflavone genistein, could be theoretically assumed with diet and they might potentiate the effect of 1,25(OH)2D3 in the immune response against cancer, although further randomized controlled trials are requested." (PMID 26301200, 2015). "For example, CYP24A1-specific inhibitor VID400, anti-CYP24A1 analogues ED-71 (Eldecalcitol) and MART-10 have exhibited potent biological effects in both in vitro and in vivo studies, including inhibition of cancer cell growth and induction of apoptosis." (PMID 40630116, 2025). "Therefore, CYP24A1 could be a potential molecular marker for cancer resistance." (PMID 36527000, 2022). "Aside from the correlations with CYP24A1, nucleoside diphosphate kinase 2, NME2, is a metastasis suppressor in many types of cancer." (PMID 35642922, 2022). "Previous studies have shown that CYP24A1 mRNA expression is not only upregulated in CRC cell lines but also in CRC samples, especially in poorly differentiated and late-stage cancers." (PMID 33791222, 2021). "A study has shown a higher level of expression of CYP24A1 mRNA and protein in CRC tissue than that in non-cancer tissue, while another study has confirmed an absence or reduced CYP24A1 expression level normal colonic mucosa." (PMID 34191826, 2021). "Following RARβ silencing, the down-regulation of cancer-related genes, ALDH1A1, CYP24A1, BIRC5, EDN1, IL-1β and PTGS2 in A549 parental cell suggest the importance of RARβ in controlling the expression of genes related to carcinogenicity." (PMID 33995625, 2021). "We then treated 2008 and Kuramochi CSCs and their corresponding bulk cancer cells with calcitriol, and analyzed expression of two VDR downstream genes SPP1 and CYP24A1, which possess vitamin D-responsive element." (PMID 29581858, 2018). "MiR-125b, which is frequently downregulated in many cancers, was shown to bind to the 3′-UTR of CYP24A1 mRNA and thereby inhibit its expression." (PMID 29657326, 2018). "Although, catabolism of vitamin D by CYP24A1 is considered as a major regulatory mechanism controlling 25(OH)D3 and 1,25(OH)2D3 concentrations, expression of other genes involved in vitamin D metabolism may influence the responsiveness of cancer cells to the treatment." (PMID 26260259, 2015). "Candidate oncogenes, ZNF-217, CYP24A1, MYBL2 and AIB2, encompassing the region analyzed by FISH, were previously reported to be amplified in other types of cancer as well." (PMID 17311676, 2007). "Yet, it is important to notice that evidences regarding increased CYP24A1 and 24,25(OH)2D3 are derived from studies on cancer tissue and cells, but not from analyses in serum." (PMID 33269020, 2020). "Furthermore, the upregulation of CYP24A1 at GI20 treatment likely increases the catabolism of 25(OH)D3 and 1,25(OH)2D3, and therefore may mitigate the anti-cancer action of the high-treatment dose." (PMID 40362248, 2025). "Moreover, tissue hypoxia (though not in cancer tissues) caused a drop in VDR, vitamin D binding protein (VDBP), and 25-hydroxylase (CYP2R1) levels while it increased CYP27B1 and CYP24A1 levels." (PMID 35406562, 2022).
cancer (continued). "Moreover, the pooled HRs for the sample size subgroup were also analyzed and both of the pooled HRs were greater than 1, indicating that the sample size did not affect the function of CYP24A1 expression in promoting survival time of cancer patients." (PMID 36527000, 2022). "CYP24A1 gene was believed to reduce the efficacy of certain anti-proliferative agents such as vitamin D and its analogues 29, and the EDN1 gene that was known to act as a neoangiogenic and mitogenic factor in several cancers 30 are the best target of cancer therapy study." (PMID 33995625, 2021). "This suggests that the overexpression of CYP24A1 in many cancer cells may not be the result of normal physiological processes regulated by calcitriol–VDR-dependent mechanisms." (PMID 29657326, 2018). "Although CYP24A1 expression is induced by calcitriol–VDR activation via negative feedback regulation, the high level of CYP24A1 expression observed in cancer cells is unlikely to be mediated by VDR activation because VDR expression and activity are downregulated in most cancer." (PMID 29657326, 2018). "Cancers which express CYP24A1 tend to be more aggressive than those which do not." (PMID 29951549, 2018). "The observed upregulation of CYP24A1 mRNA and protein after knockdown of ERβ is proposed to be one important reason for the increase of MDA-MB-231 cell invasiveness, because 1,25-dihydroxyvitamin D3 is known to reduce invasion, motility and metastasis of cancer cells." (PMID 28003019, 2016). "Moreover, the overexpression of CYP24A1 in numerous cancer cells may not be a result of normal physiological processes mediated by calcitriol–VDR-dependent mechanisms." (PMID 34208589, 2021). "However, the extraordinarily high level of CYP24A1 activity in highly malignant cancers probably does not result from up-regulation by the 1,25-(OH)2D3/VDR system but may be due to overexpression of the gene." (PMID 24213465, 2012). "Activities of the enzymes that degrade (CYP24A1) and activate vitamin D (CYP27B1) were suppressed in MCSCs, but not in cancer cells propagated under high attachment conditions." (PMID 23341935, 2013).
infection (10 papers, 2010 to 2025). The state of being infected such as from the introduction of a foreign agent such as serum, vaccine, antigenic substance or organism. "Conversely, Cyp27B1 and Cyp24A1 expression was higher at day 2 and day 4 post-infection than in the uninfected lung." (PMID 35893921, 2022). "Overall, infection status influenced expression of CYP24A1, also known as 24-hydroxylase, with an observable decrease in expression for clinical cows compared to controls (P = 0.12) and subclinical cows (P = 0.06)." (PMID 35111692, 2021). "This may suggest that upon activation of the host cell during infection, 1,25(OH)2D3 may downregulate CYP24A1 inactivation of 1,25(OH)2D3 to keep active vitamin D3 concentrations high for other regulatory signaling events within the cell." (PMID 35111692, 2021). "Our study also saw MPS activation increase CYP24A1 expression relative to non-stimulated controls and addition of 1,25(OH)2D3 dampen its upregulation for all infection status groups." (PMID 35211544, 2022). "The expression of the Vdr, Cyp27B1, Cyp24A1 was not different in D− and D++ mice at day 6 post-infection." (PMID 35893921, 2022). "Different studies have found an upregulation of CYP24A1 mRNA in bronchial epithelial after infection or triggered by inflammatory cytokines, others did not observe important changes." (PMID 32493333, 2020). "CYP24A1 showed no significant level of variation among infection status groups." (PMID 36816182, 2023). "In the present study, levels of CYP24A1 and CYP27B1 were not affected by infection status, except for lower CYP27B1 expression for subclinical cows compared to clinicals." (PMID 35211544, 2022).
kidney disease (6 papers, 2016 to 2024). "Thus, Cyp24a1 KO rats treated with vitamin D, 25(OH)D3, or 1,25(OH)2D3 could be used as models of renal diseases originating from CYP24A1 dysfunction, although further studies are needed." (PMID 33865853, 2021). "Thus, Cyp24a1 KO rats could represent an important model for studying renal diseases originating from CYP24A1 dysfunction." (PMID 33865853, 2021).
colonic polyps (3 papers, 2020 to 2025). "Furthermore, CYP24A1 polymorphism rs6068816 AX carriers were significantly associated with the intestinal ulcer in patients with CRC (P = 0.04, OR = 2.24, 95%CI: 1.05–4.77)." (PMID 34191826, 2021).
adenocarcinoma (2 papers, 2014 to 2025). A common cancer characterized by the presence of malignant glandular cells. "In this study, we demonstrate that its precursor, 25(OH)D3, decreased cell count and viability, induced apoptotic cell death, and upregulated the gene and protein expression of VDMS enzymes (CYP27B1 and CYP24A1) and receptor (VDR) in the HeLa adenocarcinoma cell line." (PMID 40362248, 2025). "They found highest cyp24a1 mRNA expression in benign colorectal lesions compared to normal colonic tissue and adenocarcinomas, while cyp24a1 protein expression was highest in advanced adenocarcinomas as compared to early stages or normal tissue." (PMID 24416388, 2014).
calcium metabolism disorders (2 papers, 2021 to 2023). "CYP24A1 is an enzyme responsible for deactivating vitamin D precursor (25(OH)D) and active vitamin D (1α,25(OH)2D), and its dysregulation leads to vitamin D and calcium metabolism disorders." (PMID 37414755, 2023).
colon (2 papers, 2020 to 2021). "Some studies have shown that high CYP24A1 can induce colon carcinogenesis, but no current studies have indicated how high it would have to be to do so." (PMID 32422882, 2020).
genetic disease (2 papers, 2025). "The case exemplifies late onset genetic disease secondary to CYP24A1 loss of function, likely triggered by excessive vitamin D supplementation." (PMID 40917505, 2025).
gastrointestinal disease (1 paper, 2025). A disease that occurs in the gastrointestinal system, excluding the hepatobiliary system. "Altered intestinal expression of CYP24A1 has been implicated in gastrointestinal diseases through its effects on local vitamin D catabolism, epithelial barrier function, and immune signaling." (PMID 41228419, 2025). "We also examine how CYP24A1 is altered in gastrointestinal diseases and consider its potential as a therapeutic target." (PMID 41228419, 2025).
inflammation (1 paper, 2023). Aberrant reaction of the microcirculation characterized by movement of fluid and leukocytes from the blood into extravascular tissues. "In conclusion, this study showed that the VDR expression decreased in the islets of Langerhans during pancreatic inflammation and demonstrated the expression of CYP24A1 and CYP27B1 in canine pancreases for the first time." (PMID 37808100, 2023).
CYP24A1 also shares sentences with these, for which no sentence is quoted: glaucoma (12 papers); epilepsy (5); cerebral edema (4); hyperphosphatemia (4); Hypocalcemia (4); retinitis pigmentosa (4); altitude sickness (2); Alzheimer disease (2); autoimmune disease (2); autosomal dominant tubulointerstitial kidney disease (2); Calcium nephrolithiasis (2); Dent disease (2); Failure to thrive (2); Hyperglycemia (2); parathyroid adenoma (2); periodontitis (2); psoriasis (2); Renal cyst (2); urinary stones (2); viral infection (2); Acidosis (1); acute coronary syndrome (1); acute myeloid leukemia (1); Alagille syndrome (1); allergic rhinitis (1); Allergy (1); anal carcinoma (1); anemia (1); ankylosing spondylitis (1); APRT deficiency (1).
A further 84 diseases each share a sentence with CYP24A1 in 1 paper.